MUC1 (mucin 1, cell surface associated)
Diseases named in the same sentence as MUC1 in open-access papers (continued):
Sharing a sentence is not in itself a finding about the gene and the disease.
pancreatic cancer (continued). "Previous studies have demonstrated aberrant expression of both MUC1 and EGFR in pancreatic cancer." (PMID 29987260, 2018). "The blocking of MUC1-CT downstream signaling in SMAD4 - negative pancreatic cancer cell line reduces the effects previously seen in the MUC1-high expressing cells, establishing the importance of MUC1-CT." (PMID 29467938, 2018). "Treatment with the commercially available anti-MUC1 antibody GP1.4 resulted in the inhibition of proliferation and migration of pancreatic cancer cells by activating the internalization of EGFR which leads to sequestration of surface receptors and repression of ERK phosphorylation." (PMID 29987260, 2018). "For pancreatic cancer, PSCA, Tn glycan on the mucin 1 (MUC1), and mesothelin are all overexpressed." (PMID 28239502, 2017). "Intriguingly, Gal-3 is able to stabilize MUC4 but not MUC1 mRNA, in our pancreatic cancer cell model." (PMID 28262838, 2017). "MUC-1-specific autologous T cells, isolated from patient peripheral blood mononuclear cells (PBMCs), were expanded by incubation with a MUC-1-presenting cell line prior to administration to pancreatic cancer patients." (PMID 27141395, 2016). "Although, tumor-associated MUC1 has been reported to be immunosuppressive, its role in MDSC generation and function in pancreatic cancer has never been explored." (PMID 24605110, 2014). "AIT with MUC1-DCs and MUC1-CTLs plus GEM may be a feasible and effective treatment for pancreatic cancer." (PMID 24947606, 2014). "Analyses of the DNA methylation status of MUC1, MUC2 and MUC4 were useful for differential diagnosis of human pancreatic neoplasms, with specificity and sensitivity of 87% and 80% for PDAC; 100% and 88% for intestinal-type IPMN; and 88% and 77% for gastric-type IPMN, respectively." (PMID 24714692, 2014). "In our present study, analyses of the DNA methylation status of MUC1, MUC2 and MUC4 in pancreatic juices were useful for differential diagnosis of human pancreatic neoplasms i.e. PDAC, intestinal-type IPMN and gastric-type IPMN, with high specificity and sensitivity." (PMID 24714692, 2014). "MUC1 (mucin-1, CD227) is a polymorphic, glycosylated type I transmembrane protein present in glandular epithelium of different tissues (pancreas, breast, lung) and overexpressed (aberrantly glycosylated) in 90% of pancreatic cancers." (PMID 23509731, 2013). "We examined S2.013 pancreatic cancer cells, with and without overexpression of MUC1, and identified 103 microRNAs altered by MUC1 expression." (PMID 24143167, 2013). "Here we report that there was not a correlation between relative levels of MUC1 and miR-200c in a panel of pancreatic cancer cell lines or matched sets of primary tumor and metastases." (PMID 24143167, 2013). "Lack of MUC1 has been correlated with decreased proliferation, invasion, and mitotic rates both in vivo and in vitro in pancreatic cancer." (PMID 22912777, 2012). "They investigated whether the combination of MUC1+cytology and MUC5AC+cytology could provide higher sensitivity and accuracy in a pancreatic cancer diagnosis in comparison with only a cytologic diagnosis." (PMID 23197977, 2012). "The expression of MUC1 mRNA was found to be significantly higher in all pancreatic cancer cell lines than in the non-tumorigenic human pancreatic ductal cells (HPDEC)." (PMID 22912777, 2012). "This study validates MUC1 and MSLN as biomarkers of aggressive pancreatic cancer biology." (PMID 22792233, 2012). "Survival of breast and pancreatic carcinoma patients who had antibodies specific for MUC1 was longer than the survival of those without MUC1-specific antibodies." (PMID 23028615, 2012). "In our previous study we found that over 90% of primary pancreatic tumors expressed MUC1 while 95% of normal pancreas tissues did not." (PMID 24212784, 2011). "Another question to address is whether the decrease of MUC1 and MUC4 expression could contribute to the AP-2α-induced sensitisation of pancreatic cancer cells to gemcitabine." (PMID 19672266, 2009).
pancreatic cancer (continued). "The MUC-1 antigen is identified in pancreatic carcinomas and precursor lesions, but is not detected in normal pancreas." (PMID 19956730, 2009). "In this study, we found that over 90% of primary pancreatic tumours expressed MUC1, while the majority of normal pancreases did not." (PMID 15599383, 2004). "In this model, CD4+ T cells were critical for rejection of MUC1-positive tumours, whereas other studies suggest that CD8+ T cells are required for MUC1-specific immunity against MUC1-positive pancreatic carcinoma." (PMID 12966437, 2003). "MUC1 carrying the monosialyl and disialyl T antigen has been identified as a counter-receptor for MAG (Siglec-4), and it was shown that their adhesive interaction might contribute to the pancreatic cancer invasion of the space surrounding a nerve." (PMID 38611013, 2024). "For example, MUC1 and MUC5AC affect E‐cadherin and β‐catenin complexes, thereby promoting the proliferation, invasion, and metastasis of ovarian and gastric cancer cells; in contrast, MUC4 gene deletion in pancreatic cancer cells inhibits tumor progression by regulating apoptosis and cell cycle." (PMID 37666495, 2024). "Furthermore, we confirmed that GCNT3 expression correlates with MUC1 and MUC5AC expression (Pearsons’ coefficient (Cor) 0,48 and 0,51 respectively) and that they were all biomarkers of worse prognosis in pancreatic cancer patients (GCNT3, HR = 1.64), (MUC1, HR = 2.56), (MUC5AC, HR = 2.04)." (PMID 37996891, 2023). "In addition, MUC1 also plays an important role in ovarian cancer, non-small cell lung cancer and pancreatic cancer." (PMID 35879749, 2022). "Interestingly, we also found that MUC4EGF1+2 regulates the expression of other membrane-bound mucins such as MUC1 and MUC16, two membrane-bound mucins that we recently described as being a potent molecular signature for bad prognosis in pancreatic cancer and overall survival." (PMID 34830899, 2021). "MUC1 and MUC4 are reported to be involved in stemness which confers drug resistance in cancer cells, implicating that overexpression of IL-17RB may lead to enhancement of chemotherapy resistance through upregulation of these genes in pancreatic cancer cells." (PMID 33082357, 2020). "Importantly, MUC1 and MUC4 modulate chemoresistance of pancreatic cancer cell lines in vitro." (PMID 32707920, 2020). "Validation of the method using clinical samples from pancreatic cancer patients with EGFR (epidermal growth factor receptor), EpCAM (epithelial cell adhesion molecule), HER2, and MUC1 (mucin-1) antibodies, indicated that the method could be used for profiling scarce cells from clinical samples." (PMID 31762967, 2019). "Taken together, the anti-hMUC1 monoclonal antibody suppressed EGF-mediated signaling in MUC1 expressing pancreatic tumor cells even though we could not detect its growth-suppressive effect in vitro." (PMID 29987260, 2018). "In pancreatic cancer, silencing of galectin-3 has shown to enhance the cell surface interaction between MUC1 and EGFR in the absence of EGF stimulation and reduced the rate of endocytosis of MUC1-EGFR complex which leads to the noticeable cell surface localization of MUC1." (PMID 25261375, 2014). "Indeed the T lymphocytes obtained from a pancreatic cancer patient did not recognize an MUC1 peptide presented by an MHC molecule, but rather, directly, the hypoglycosylated core of MUC1." (PMID 23509794, 2013). "In our study, proliferation rate was not affected, although invasive and adhesive activities of SW1990 after MUC5AC inhibition were decreased markedly, suggesting that MUC5AC, similarly to MUC1 or MUC4, might have potential to accelerate progression of pancreatic cancer." (PMID 20492722, 2010). "Although KL-6 is considered to be co-expressed with membrane-bound MUC1 in tumor tissues, a previous study indicated its potential role in facilitating invasion and metastasis in pancreatic cancer; however, its functional significance in other malignancies remains unclear." (PMID 41416421, 2026).
pancreatic cancer (continued). "For example, it was shown that CA19-9 expression in MUC5AC and MUC1 proteins may be increased, independently of protein elevation, and that the combined measurement of MUC5AC and CA19-9 presents better performance and improved specificity to differentiate pancreatic cancer subjects from controls." (PMID 37455827, 2023). "MUC1 may have an important role in disc aging and degeneration by acting as a regulator in the hypoxic environment, helping disc cells to survive under hypoxic conditions by stabilization and by activation of HIF-1α as previously recognized in pancreatic cancer cells." (PMID 28482827, 2017). "Therefore, ALB was nontoxic to pancreatic cancer cells on functional targeting of EpCAM or muc1." (PMID 27886058, 2016). "Though the downstream pathways of cell death as a consequence of MUC1 inhibition have been studied in a number of cancers, the mechanism of initiation of mitochondrial depolarization (following MUC1 inhibition) leading to activation of apoptotic pathways is not clear in pancreatic cancer." (PMID 22912777, 2012). "Five days after stimulation, the T cells were used in a CTL assay using PC3 (human prostate carcinoma, MUC1+, HLA-A24+) as a target and ASPC-1 (human pancreatic carcinoma, MUC1+, HLA-A24NEG) as a negative control." (PMID 27192116, 2016). "Human pancreatic cancer cells revealed high and relatively moderate MUC1 levels for Capan-1 and HPAF-II, respectively, compared to MUC1 negative control (U-87 MG glioblastoma) that showed relatively non-specific anti-MUC1 uptake." (PMID 17912239, 2007). "Here we unveil for the first time that pancreatic cancer cells (PANC-1) and secreted exosomes express MUC1 bearing cancer-relevant dynamic epitopes recognized specifically by an anti-MUC1 antibody (SN-131), which binds specifically core 1 but not core 2 type O-glycans found in normal cells." (PMID 37547453, 2023). "MUC1 and MUC5 had no predictive value for the prognosis of pancreatic cancer patients." (PMID 35709153, 2022). "In addition, MUC1 can increase the carbon flux of the non-oxidative pentose phosphate pathway (PPP) and pyrimidine synthesis pathway of pancreatic cancer cells by promoting the expression of HIF-1α, leading to gemcitabine resistance." (PMID 35879749, 2022). "However, due to the non-specificity of most of the MUC1 antibodies, we believe that TAB004 can improve the specific visualization of pancreatic tumor." (PMID 29462213, 2018).
lung carcinoma (194 papers, 2005 to 2026). "CV9202 is an RNA mixture encoding six overexpressed antigens in lung cancer cells, including MUC1, NY-ESO-1, MAGE-C2, MAGE-C1, Survivin and 5T4." (PMID 39179939, 2025). "The upregulation of MUC1 is a hallmark of lung cancer, particularly in NSCLC, with its expression level closely associated with tumor aggressiveness, dissemination, and recurrence." (PMID 40655139, 2025). "For tumors without viral etiologies, vaccines targeting cancer-associated mucin 1 (MUC1) have been evaluated in patients with colon adenoma as a premalignant disease or resected non–small cell lung cancer." (PMID 34882581, 2022). "One of the proteins that has been associated with chemoresistance in lung cancer is Mucin-1 (MUC1), found to be overexpressed in NSCLC and correlated with poor survival." (PMID 32575472, 2020). "An increased KL-6 level in lung carcinoma patients has been associated with a poor prognosis and downregulation of the MUC1 was claimed to inhibit the non-small cell lung carcinoma progression." (PMID 32948202, 2020). "MUC1 is aberrantly overexpressed by cancer cells, including lung carcinomas, where its overexpression is associated with poor survival." (PMID 29186029, 2017). "Further, Muc1-deficient mice, or treatment of A549 lung cancer cells with the MUC1-CT inhibitory synthetic peptide, GO-201, increased epiregulin production by the cells." (PMID 29186029, 2017). "Recent evidence demonstrates that the expression of pro-oncogenic mucin, MUC1 is elevated in response to inflammation in airway epithelial cells and is associated with lung cancer development." (PMID 27276704, 2016). "Morover, a positive association between the serum levels of MUC1/ KL-6 and risk of lung cancer was also reported." (PMID 26930275, 2016). "We found that MUC1 was overexpressed in lung cancer patients, which was associated with poor survival rates." (PMID 27276704, 2016). "Elevated MUC1 expression has been reported in inflammatory lung macrophages and is associated with lung cancer development." (PMID 27276704, 2016). "In this study we set out to examine the role of MUC1 in TAMs and its association with the generation of lung cancer stem cells." (PMID 27276704, 2016). "For example, expression of MUC1 is associated with patient outcome and MUC1 is being pursued as a therapeutic target in both breast and lung cancer." (PMID 25829177, 2015). "MUC1 encodes a membrane-bound protein that is a member of the mucin family; increases in MUC1 protein levels are associated with poor prognosis of non–small cell lung cancer." (PMID 23210427, 2012). "One of the molecule candidates to target cancers is Mucin 1 (Muc1), a glycoprotein expressed on the surface of epithelial cells, and its overexpression is often associated with tumorigenesis and metastases, including breast, pancreatic and lung cancers." (PMID 39105847, 2024). "Interestingly, it has been reported that increased EREG expression by Mucin-1 (MUC1) deficiency in fibroblasts and epithelial cells accelerated lung cancer development through the EGFR/AKT pathway." (PMID 38673992, 2024). "Their results suggest that MUC1 deficiency in fibroblasts and lung cancer cells increases the EREG production that activates EGFR signaling to compensate for the MUC1 loss, thereby promoting the activation of the EGFR and AKT pathways during lung carcinogenesis." (PMID 38398101, 2024). "Interestingly, following treatment with erlotinib in combination with the WT1/MUC1-DC vaccine, the tumor was undetectable by CT analysis for at least 587 days after treatment in a patient with lung cancer with EGFR-mutated adenocarcinoma." (PMID 38336778, 2024). "To determine whether our lung cancer model could reproduce the in vivo characteristics of lung cancer, we focused on mucin 1 (MUC-1), a protein associated with lung carcinoma." (PMID 37434755, 2023).
lung carcinoma (continued). "MUC1 is identified as one of the most prevalent cancer-associated antigens that are involved in the bio-signaling tumor cell survival, proliferation, and progression in many forms of cancers including lung cancer." (PMID 34138386, 2021). "A recent report showed that glycoprotein MUC1-associated EVs increased in lung cancer sera." (PMID 32878320, 2020). "The association between MUC1 overexpression and tumorigenesis of lung and other cancers has been demonstrated in hamster and mouse models, and these findings have been extrapolated to human lung cancer." (PMID 30479696, 2018). "Also, the conjugation of the MUC1 peptide (tumor-associated antigen in lung cancer) to the surface of a liposome with a composition of DPP-DPPG-Chol (3:1:0.25, molar ratio) containing MPL A (1% w/w of the total lipids) elicited strong CTL response." (PMID 29045460, 2017). "Interestingly, MUC1 expression levels were reported to be associated with response to EGFR inhibitors in lung cancer patients." (PMID 22457794, 2012). "The epigenetic repression of myelin and lymphocyte protein gene (MAL) and over-expression of MUC1 protein are two well-documented hallmarks of various carcinomas including lung cancer." (PMID 42038033, 2026). "Lung cancer: A phase I trial exists that studies six patients with stage IIIB-IV non-small-cell lung cancer (NSCLC) treated with PD-1 KO anti-MUC-1 CAR T cells." (PMID 41354926, 2025). "Clinical trials are underway using MUC1-based vaccine to prevent lung cancer in current and former smokers and in preventing recurrence of colon polyps in patients with advanced adenomas." (PMID 40437549, 2025). "MUC1, an oncogenic molecule, promotes the occurrence, development, and metastasis of lung cancer through multiple mechanisms." (PMID 41041313, 2025). "Extensive research has been conducted on the role of MUC family genes in lung cancer, particularly MUC1 and MUC21." (PMID 41409294, 2025). "Some of the selected antigens are used as diagnostic markers in lung cancer subtypes (TTF-1, MUC-1, HER, cytokeratin, and CD56), others as prognostic, proliferative, or immunosuppressive targets." (PMID 39941799, 2025). "Given its expression on the surface of cells in several cancers, it has been exploited for nanoparticle delivery in conjunction with fractionated radiation therapy employing MUC1-conjugated nanoparticles in breast and lung cancer." (PMID 39767713, 2024). "Extensive studies have highlighted the markedly increased presence of MUC1 in lung cancer specimens compared to normal tissues." (PMID 38622705, 2024). "Numerous clinical trials (NCT02587689, NCT03356808, NCT03198052, NCT03525782, NCT04842812) are currently underway, with the aim of utilizing CAR-T cells targeting MUC1 to treat lung cancer." (PMID 38622705, 2024). "Our data showed that only a high dose of AICAR treatment (3 mM) reduced MUC1-CT protein expression (p < 0.05), indicating that AICAR treatment can also block MUC1-CT expression in MUC1 highly abundant lung cancer cell lines." (PMID 36810913, 2023). "Like CEA, Mucin 1 (MUC1) is also highly expressed in lung cancer, promotes metastasis, and is thus an exciting target for ACT against lung cancer." (PMID 36810079, 2023). "Collectively, these data suggest that mutant EGFR TL induces MUC1/MUC1-CT expression in lung cancer tissues." (PMID 36810913, 2023). "CAR-T cells targeting EGFR variant III, mesothelin, Erythropoietin-producing hepatocellular carcinoma A2 (EphA2), Delta-like 3 (DLL3), PSCA- and MUC-1, and PD-L1 have shown significant antitumor effects against lung cancer cells in vitro and in vivo." (PMID 37420216, 2023).